MYCN (MYCN proto-oncogene, bHLH transcription factor)
Diseases named in the same sentence as MYCN in open-access papers (continued):
Sharing a sentence is not in itself a finding about the gene and the disease.
neuroblastoma (continued). "GATA3 has also been shown to be part of the core transcriptional regulatory circuitry in MYCN-amplified neuroblastoma cells and plays an oncogenic role in high-grade serous ovarian carcinoma." (PMID 36856111, 2023). "The predictions of MYCN amplification and overall survival of neuroblastoma based on ZNF436 expression were validated in TARGET, GSE16476 and GSE62564 datasets." (PMID 37904225, 2023). "Using CRISPR‐activation screens in ferroptosis hypersensitive cells, we identify the selenoprotein P (SELENOP) receptor, LRP8, as a key determinant protecting MYCN‐amplified neuroblastoma cells from ferroptosis." (PMID 37435859, 2023). "PROTACs elicited Aurora-A degradation at low nanomolar potency in leukemic cells and should now be considered as a therapeutic option in MYCN-amplified neuroblastoma." (PMID 37414143, 2023). "In this minireview, I summarize the recent progress in understanding the functional role of MYCN and its regulatory partners in neuroblastoma metastasis." (PMID 37274289, 2023). "Known neuroblastoma-related genes such as MYCN, TERT, ODC1, CDK4, and MDM2 were recurrently affected by different classes of complex rearrangements including ecDNA, chromothripsis, and CnCs." (PMID 37868040, 2023). "In a different study, G9a inhibitor, UNC0638, was found to increase apoptosis in MYCN-amplified neuroblastoma cells." (PMID 36899853, 2023). "Embryonal tumors with MYCN deregulation such as neuroblastoma, retinoblastoma, medulloblastoma, Wilms tumor, and rhabdomyosarcoma are highly malignant and are often less amenable to targeted therapies." (PMID 37046804, 2023). "The low‐density lipoprotein receptor (LRP8) was identified as a critical suppressor of ferroptosis in MYCN‐amplified neuroblastoma." (PMID 37435859, 2023). "In neuroblastoma, MYCN amplification directly upregulates ALYREF transcription and ALYREF regulates MYCN stability in a forward feedback loop." (PMID 37537569, 2023). "Neuroblastomas that had been clinically subtyped as MYCN amplified at diagnosis displayed a highly variable MYCN signature at relapse (subtype T077)." (PMID 36932241, 2023). "In neuroblastoma, this phenotypic conversion primarily relies, among others, on the overexpression of MYCN oncoprotein, which accounts for the altered transcriptional regulation of dozens of genes." (PMID 37835497, 2023). "Yet, we show that oncogenic MYCN levels in neuroblastoma act through DHX9 to globally suppress circRNA expression, and present evidence for the same activity in the related embryonal tumor, medulloblastoma, demonstrating the importance of this factor." (PMID 37402719, 2023). "In fact, the 1p36 deletion is strongly correlated with MYCN amplification in patients with neuroblastoma." (PMID 36831211, 2023). "In many cases, neuroblastoma phenotypes are characterized by the aberrant expression of MYCN and its downstream interrelationships with critical metabolism-related genes." (PMID 37835497, 2023). "The most prominent MYCN-driven tumor models mimic human neuroblastoma, in which MYCN expression, driven by tyrosine-hydroxylase (TH)- or dopamine-β-hydroxylase- (Dbh)-cre, leads to the development of aggressive tumors, modeling the human disease." (PMID 38001143, 2023). "I explored eight different MYCN regulatory networks and sought to determine the mechanisms by which this oncogene influences neuroblastoma metastasis." (PMID 37274289, 2023). "Much research has found that MYCN gene amplification, chromosome 1p36 and 11q deletions can predict stage and prognosis in patients with neuroblastoma." (PMID 37035169, 2023). "Specifically, the expression of XIAP was higher in MYCN-amplified neuroblastoma cells compared with non–MYCN-amplified cells (positive correlation with R2 = 0.76)." (PMID 37874199, 2023). "MiR-15a-5p, miR-15B-5p, and miR-16-5p can intervene in neuroblastoma by inhibiting the expression of MYCN." (PMID 37426487, 2023).
neuroblastoma (continued). "Combinations of ZNF436, MYCN amplification or age at diagnosis achieved better prognosis in neuroblastoma." (PMID 37904225, 2023). "This suggests that disulfiram treatment significantly delayed MYCN-amplified neuroblastoma progression." (PMID 37777587, 2023). "MYCN thus plays a significant role in neuroblastoma biology and is the most important target for therapy." (PMID 37274289, 2023). "Here we present the global circRNA landscape in neuroblastoma, which is shaped by oncogenic MYCN mediated by the DHX9 RNA helicase." (PMID 37402719, 2023). "Ubiquitin-specific protease 7 (USP-7; also known as HAUSP) has been demonstrated asana MYCN function regulator in neuroblastoma." (PMID 37298148, 2023). "XIAP degradation is sufficient to kill MYCN-amplified neuroblastoma which overexpresses and relies on XIAP as a brake against cell death, without affecting normal cells." (PMID 37874199, 2023). "It was shown that MYCN-amplified neuroblastoma cells expressing LIN28B had a higher metastatic potential." (PMID 37304235, 2023). "Given their positive feedback, there is a possibility that ALK/MYCN cooperativity is involved in the oncogenic metabolic transformation (e.g., elevated glucose uptake/glycolysis and lipid synthesis) of neuroblastoma." (PMID 37414143, 2023). "Combined PI3K and BRD4 inhibition also shows promise, suppressing MYCN expression and inhibiting neuroblastoma cell growth and metastasis both in vitro and in vivo." (PMID 38087370, 2023). "Histologically, this specific subgroup of retinoblastoma shares more similarities with MYCN-amplified neuroblastomas than classical retinoblastomas, but molecular mechanisms driving its onset have only begun to be explored." (PMID 36982482, 2023). "In a recent study, MYCN was found to mediate cysteine addiction, and MYCN-amplified neuroblastoma cells were more prone to lipid peroxidation and ferroptosis when cysteine was depleted." (PMID 37460542, 2023). "Disulfiram shifted neuroblastoma transcriptome, decreasing MYCN levels and activating neuronal differentiation." (PMID 37777587, 2023). "In our study, many neuroblastoma cell lines with MYCN amplification exhibited increased expression of KLF4, indicating a potential contribution to the cell cycle dysregulation and the transformation process underlying neuroblastoma development." (PMID 37835497, 2023). "Evidently, our results underscore that MYCN is substantially committed to metabolic rewiring in neuroblastoma cells through its attachment to transcriptional regulatory cis-elements that neighbor metabolism-related TF-encoding genes." (PMID 37835497, 2023). "We find that the LRP8 dependency in MYCN‐amplified neuroblastomas is partially due to the limited activity of alternative selenium transporters, specifically system Xc−." (PMID 37435859, 2023). "In contrast, we found that pan-IAP antagonists tested in this study including LCL-161, CUDC-427, Debio1143, and BV6 targeted mainly c-IAPs, induced high toxicity in normal cells and were ineffective toward XIAP-dependent, MYCN-amplified neuroblastomas." (PMID 37874199, 2023). "XIAP, the most potent mammalian inhibitor of apoptosis protein (IAP), critically restricts developmental culling of sympathetic neuronal progenitors, and is correspondingly overexpressed in most MYCN-amplified neuroblastoma tumors." (PMID 37874199, 2023). "In MYCN-amplified neuroblastoma patient-derived xenografts, A4 significantly prolonged survival as a single agent, and demonstrated synergism with standard-of-care agents to reduce their effective required doses 3- to 6-fold." (PMID 37874199, 2023). "In this study, we characterized a Swedish neuroblastoma cohort with the focus on telomere maintenance mechanisms (TMMs), i.e., MYCN amplification and the juxtapositioning of TERT and ATRX aberrations." (PMID 38136279, 2023).
neuroblastoma (continued). "CX3, linked to defective HRR, was most frequent in high-risk non-MYCN-amplified patients (p < 2.1 × 10−2), further corroborating the role of deficient HRR as a risk-group-defining mutational process in neuroblastoma." (PMID 37868040, 2023). "In contrast, the only solid tumors with noticeable sensitivity to venetoclax were SCLC and MYCN-amplified neuroblastoma, and there is an on-going clinical trial with venetoclax for neuroblastoma (NCT04029688)." (PMID 37685889, 2023). "The embryonal neoplasms with MYCN (myelocytomatosis-neuroblastoma derived) protooncogene amplification are predominantly malignant and show distinct characteristic features." (PMID 37046804, 2023). "Further studies in this regard led Cui and colleagues to establish a link between MYCN and the death receptor apoptotic pathways (involves Caspase-8) in neuroblastoma." (PMID 37274289, 2023). "EUR patients were slightly more frequently observed in neuroblastoma MYCN-A (93.3%) than in MYCN-NA (74.7%) cases." (PMID 38318504, 2023). "Additionally, Notch2, one of the MK receptors, was found to contribute to neuroblastoma (NB) tumorigenesis through Notch-HES1 signaling in an MK-deficient MYCN transgenic mice model for NB." (PMID 37835544, 2023). "Oncogene MYCN is closely related with malignant progression and poor prognosis of neuroblastoma (NB)." (PMID 37741985, 2023). "In MYCN-amplified neuroblastoma, SGOC metabolism is very active in supplying glucose-derived carbon for serine and glycine synthesis and presents a MYCN-dependent metabolic vulnerability." (PMID 37147729, 2023). "It has also been proved that cancer-suppressing miRNAs inhibit the expression of MYCN and the proliferation of neuroblastoma." (PMID 37592273, 2023). "For neuroblastoma, it is known that MYCN amplification is a feature of aggressive disease and that this in turn can upregulate E2F1 and MCM2." (PMID 37046768, 2023). "This evidence is consistent with the finding that PLK1 inhibition by volasertib leads to the stabilization of the ubiquitin ligase Fbxw7 and the degradation of its downstream target N-Myc in MYCN-overexpressing neuroblastoma cells." (PMID 36902175, 2023). "As LIG4 acts as part of mainstream NHEJ, we investigated the possible implication of insensitivity to DNA-PKi in MYCN-amplified neuroblastomas." (PMID 37240360, 2023). "GREB1, adjacent to the MYCN amplicon, has crucial pro-oncogenic functions independently of MYCN in MYCN-amplified neuroblastoma." (PMID 37611092, 2023). "Studying the paravertebral ganglia during the precancerous phase in TH-MYCN mice offers a valuable model to unravel the molecular mechanisms of tumor initiation in MYCN-driven neuroblastoma." (PMID 37958555, 2023). "The outcome of this comparative assessment sharply illustrates strong correlation between the genomic distribution of MYCN oncoprotein with metabolism-related processes in neuroblastoma cells." (PMID 37835497, 2023). "Analysis of human neuroblastoma tumor cohorts showed a strong correlation between dysregulated mitosis and features of MYCN amplification, such as MYC(N) transcriptional activity, poor overall survival, and other clinical predictors of aggressive disease." (PMID 37958555, 2023). "A few recent papers describe the role of CT-based radiogenomics to predict MYCN amplification in patients presenting with neuroblastoma." (PMID 36063183, 2023). "Functional analysis revealed the association among STMN1 suppression, cellular viability, and endogenous or exogenous MYCN expression in neuroblastoma cell lines." (PMID 37760452, 2023). "In this study, we have assessed disulfiram’s effects on neuroblastoma using in vitro and in vivo models, focusing on how it modulates the neuroblast transcriptome and epigenome, particularly via MYCN and KAT2A." (PMID 37777587, 2023). "This established feedback loop is crucial for increasing the amino acid availability and, consequently, sustaining MYCN-mediated growth in neuroblastoma cells." (PMID 37835497, 2023).
neuroblastoma (continued). "Increased expression and stabilization of HIF2α appears to contribute to a more aggressive and undifferentiated phenotype in both adrenal neoplasms, whereas MYCN amplification is a valuable prognostic marker in neuroblastoma." (PMID 37361539, 2023). "Mechanistically, MYCN activates Aurora-A on the chromatin of neuroblastoma cells, where it phosphorylates S10 of histone H3 during the DNA-replicating S-phase of the cell cycle." (PMID 37414143, 2023). "The MYCN gain was found in six out of ten neuroblastomas analyzed, four out of fourteen in Wilms tumors analyzed and six out of nine sarcomas analyzed." (PMID 37189699, 2023). "Beyond Burkitt lymphoma, WDR5 is thought to play a pro-tumorigenic role in various other cancers, including high-risk neuroblastoma, which is associated with amplification of the N-MYC gene, MYCN." (PMID 37336886, 2023). "We demonstrate a global suppressive effect of oncogenic MYCN levels mediated by the DHX9 RNA helicase on circRNA expression in neuroblastoma and a second childhood embryonal tumor, medulloblastoma." (PMID 37402719, 2023). "This is in line with previously published data showing increased sensitivity of cancer cells with high MYC/MYCN-expression to PARPi including glioblastoma stem-like cells, neuroblastoma, multiple myeloma and medulloblastoma cells in vivo and in vitro." (PMID 37783879, 2023). "Let us consider the oncogene MYCN, which is a transcription factor that is amplified in human neuroblastoma and is related to its prognosis." (PMID 37514113, 2023). "Elevated DLST expression among high-risk neuroblastoma patients correlated with an enrichment of genes within the OXPHOS network, while OXPHOS inhibition perturbed the aggressive properties of MYCN-amplified neuroblastoma xenografts." (PMID 37414143, 2023). "The deletion (KO) of IGF2BP1 consistently reduced MYCN protein and mRNA expression in three neuroblastoma cell lines." (PMID 37246217, 2023). "We reveal a novel, druggable neuroblastoma oncogene circuit settling on strong, transcriptional/post-transcriptional synergy of MYCN and IGF2BP1." (PMID 37246217, 2023). "In neuroblastoma cell lines, MYCN was co-amplified with distal enhancer e4, and chromatin capture analysis indicated that e4 interacted with the promoter of MYCN to enhance MYCN expression." (PMID 37448518, 2023). "In another study with a larger sample size, the radiomics logistic regression model was also successful in predicting MYCN amplification status in pediatric abdominal neuroblastoma." (PMID 37316589, 2023). "MYCN amplification is a significant driver in neuroblastoma and is indicative of a poor prognosis in early-stage tumors." (PMID 37239815, 2023). "Our observation that MYCN‐amplified neuroblastoma cells are highly dependent on LRP8 for selenium uptake is unanticipated, given that alternative forms and uptake mechanisms exist." (PMID 37435859, 2023). "In this study, the authors selected the 9464D neuroblastoma cell line due to a characteristic overexpression of the MYCN gene." (PMID 36987269, 2023). "This feedback loop contributes to the maintenance of high levels of both MYCN and NCYM expressions in MYCN-amplified neuroblastomas." (PMID 38074684, 2023). "The biological effects of STIRUR 41, an inhibitor of IL8-induced neutrophil chemotaxis, were tested on ACN and HTLA-230 neuroblastoma cells, the latter being characterized by high plasticity and aggressiveness due to MYCN gene amplification." (PMID 37298148, 2023).
neuroblastoma (continued). "It was also reported that MYCN-amplified neuroblastoma cells rely on the amino acid transporter ASCT2 (solute carrier family 1 member 5, SLC1A5) for the provision of glutamine, in which its expression correlates with poor patient survival." (PMID 37414143, 2023). "MYCN gene, as previously stated, plays a key regulatory function in the genesis and progression of neuroblastoma." (PMID 37745860, 2023). "As members of the Myc oncogene family (MYC, MYCN, and MYCL) have been implicated in SCLC and neuroblastoma oncogenesis, we attempted to dissect their relationship with the NE state." (PMID 37255415, 2023). "This suggested that XIAP is highly expressed in most neuroblastoma tumors and is positively correlated to MYCN amplification status." (PMID 37874199, 2023). "Formation of the Aurora-A–MYCN complex increases levels of the oncogenic transcription factor MYCN in neuroblastoma cells by abrogating its degradation through the ubiquitin proteasome system." (PMID 36601802, 2023). "MYCN amplification is frequent in high-risk patients and is utilized for patient-risk classification; however, this is not the only mechanism responsible for the disease, since non-MYCN-amplified neuroblastoma is abundantly recorded in patients." (PMID 37835497, 2023). "Very few studies have demonstrated a crucial role of MYCN and its regulatory proteins in neuroblastoma metastasis." (PMID 37274289, 2023). "Otto and colleagues found that Aurora-A was required for the growth of MYCN-amplified neuroblastoma cells." (PMID 37414143, 2023). "We found MYCN gain in the peripheral blood in 16 cases (46%); this is similar to other studies that reported 42% of 52 patients with neuroblastoma having MYCN gain." (PMID 37189699, 2023). "Public neuroblastoma single cell RNA-seq data indicated nearly exclusive expression and strong association of IGF2BP1 and MYCN expression in tumor cell populations." (PMID 37246217, 2023). "Approximately 50% of patients with neuroblastoma exhibit a high-risk phenotype (HRNB), characterized by metastases in patients >18 months of age or the presence of an amplified MYCN gene in patients of any age." (PMID 37834840, 2023). "In neuroblastoma, the TF MYCN has been recorded as dysregulated, presenting both aberrant expression and genomic abnormalities across its coding locus." (PMID 37835497, 2023). "Known prognostic factors of neuroblastoma include age at diagnosis, neuroblastoma stage and MYCN amplification." (PMID 37904225, 2023). "The other MYCN-amplified lines, SK-N-DZ and N91, had IC50 values of 806 nM and 234 nM, respectively, while the IC50 values of the non-MYCN amplified neuroblastoma cells SK-N-AS and SK-N-SH were 73 μM and 378 nM, respectively." (PMID 37777587, 2023). "Consistently, ecDNA-harboring, MYCN-amplified neuroblastomas exhibited the lowest HRDetect probability scores, an alternative measure of HRR activity, across our cohort, with a median score of 1% and no patient with a score >70%." (PMID 37868040, 2023). "Herein, we conducted alternative workflows and succeeded in addressing the interrelationship of several TFs with MYCN overexpression, in neuroblastoma." (PMID 37835497, 2023). "Correcting for this effect, we confirmed that oncogenic MYCN levels reduce circRNA biogenesis by normalizing transcript measurement to cell count in an inducible neuroblastoma cell model." (PMID 37402719, 2023). "We followed this result by assessing cell surface expression of CD49b on N2a cells, as well as on human SH-SY5Y cells, a patient-derived neuroblastoma cell line that also lacks MYCN amplification." (PMID 38095019, 2023). "We have previously identified PA2G4 as a direct protein-binding partner of MYCN and drive neuroblastoma tumorigenesis." (PMID 36980710, 2023). "ID1 and ID2 correlated positively with SNV signature SBS18, which indicates co-occurrence of DNA damage by ROS and replication slippage in MYCN-amplified neuroblastomas." (PMID 37868040, 2023).